IL21R (interleukin 21 receptor)
Diseases named in the same sentence as IL21R in open-access papers (continued):
Sharing a sentence is not in itself a finding about the gene and the disease.
breast carcinoma (6 papers, 2019 to 2023). "Another study shows that higher expression of IL21R in patients with primary HER2+ breast cancer is associated with positive effects of trastuzumab with respect to DFS, suggesting a possible role of IL21R as predictive marker for anti-HER232." (PMID 33420250, 2021). "In the selected key specific DEGs for Her2-subtype breast cancer, the expression of IL21R, IFI30, PI15, FAM189A2, and MYZAP were significantly correlated with the prognostic survival of the patients." (PMID 33644115, 2021). "In brief, the data in Her2-subtype breast cancer suggest that IL21R, IFI30, and MYZAP may be involved in the tumorigenesis to improve OS of patients with Her2-subtype breast cancer." (PMID 33644115, 2021). "IL-21R is primarily expressed in hematopoietic cells but it has also been found to exist in non-immune cells such as fibroblasts, endothelial cells, keratinocytes, Hodgkin lymphoma cells, and breast cancer cells." (PMID 30728806, 2019). "A recent study showed IL-21 and its receptor play an important role in breast cancer cells via proliferation, migration, and invasion, suggesting IL-21R could contribute to other diseases via similar mechanisms." (PMID 30728806, 2019). "IL21R (interleukin 21 receptor) knock-down may sensitize cells to anti-tumor therapy by targeting MMPs, and participate in tumor progression and metastasis in advanced breast cancer." (PMID 33644115, 2021). "In our analysis, IL21R was specifically upregulated, and this high expression predicted high RFS and OS (p < 0.05) in Her2-subtype breast cancer, which was consistent with the prognostic analysis results in all breast cancer." (PMID 33644115, 2021). "IL21R, IFI30, PI15, and FAM189A2 may be involved in recurrence of Her2-subtype breast cancer IFI30, PI15, FAM189A2, and MYZAP can be used as the specific prognostic markers for Her2-subtype breast cancer." (PMID 33644115, 2021). "A recent study also showed that IL-21 increased the proliferation of IL-21R+ MDA-231 breast cancer cells but not that of other breast cancer cells." (PMID 30728806, 2019). "The conducted research has shown that IL-21 promotes proliferation, invasion and migration of IL-21R + MDA-231 breast cancer cells, it does not show such strong properties against MCF-7 and ZR-75.1 cells, in which IL-21R expression is weak or negative." (PMID 34300224, 2021).
systemic sclerosis (6 papers, 2008 to 2023). A chronic disorder, possibly autoimmune, marked by excessive production of collagen which results in hardening and thickening of body tissues. "IL-21R mRNA was up-regulated in keratinocytes and dermal fibroblasts in biopsy specimensfrom patients with systemic sclerosis (SSc; scleroderma)." (PMID 27096200, 2016). "IL-21R expression was found to be markedly increased in systemic sclerosis patients with skin biopsies showing keratinocytes as the predominant source of IL-21R." (PMID 24757284, 2014). "IL-21R is up-regulated in patients with systemic sclerosis (SSc) and might be involved in the pathogenesis of SSc via induction of VEGF." (PMID 37881433, 2023). "In addition, the epidermis of patients with systemic sclerosis expressed IL-21R (but not IL-21)." (PMID 22030011, 2011).
type 1 diabetes (6 papers, 2015 to 2025). "Associations of IL-21R variants with extra-pancreatic autoantibodies in patients with type 1 diabetes." (PMID 40979706, 2025). "A report describing novel sequence variants in genes encoding IL-21 and the IL-21R indicates that polymorphisms within IL-21 and the IL-21 receptor are positively associated with type 1 diabetes in humans." (PMID 26416419, 2015). "In addition, findings suggest that genetic variants in the IL17RA and IL21R genes are associated with the development of Type 1 Diabetes (T1D) and the production of pancreatic and extra-pancreatic autoantibodies." (PMID 40979706, 2025). "For example, in the study of type 1 diabetes development, deficiency in IL-21R renders the nonobese diabetic (NOD) mice resistant to onset of type 1 diabetes." (PMID 35693111, 2022).
hepatocellular carcinoma (5 papers, 2020 to 2024). A malignant tumor that arises from hepatocytes. "Deletion of IL21R promoted tumour growth in mouse model of hepatocellular carcinoma (HCC) accompanied by reduced activation and expansion of antitumour lymphocytes, suggesting an anti-tumour role of IL21R in HCC." (PMID 38723244, 2024). "Although no clinical association between IL21R deficiency and liver malignancy has been described in humans, an interesting mice model demonstrated that IL21R signaling deficiency might promote hepatocellular carcinoma (HCC) growth." (PMID 32184784, 2020). "First, high expression of IL-21R on CD8+ T cells in tumors correlates positively with overall survival and lack of tumor recurrence in hepatocellular carcinoma (HCC) patients." (PMID 34721405, 2021).
parasitemia (5 papers, 2015 to 2019). "Mice deficient for either IL-21 (Il21−/−) or IL-21R (Il21r−/−) showed significantly reduced inflammatory responses following parasitic infections as compared with their WT counterparts." (PMID 31867283, 2019). "In recent years, the IL-21/IL-21R signaling axis has been implicated in the regulation of immunity and the pathogenesis in several bacterial, viral, fungal, and parasitic infections." (PMID 31867283, 2019). "Similar to μMT mice, P. yoelii XNL infection of IL21R-/- mice was lethal and this was associated with impaired control of parasitemia and a concomitant increase in the severity of SMA." (PMID 25996913, 2015). "It has been suggested that the roles played by the IL-21/IL-21R signaling axis is context-dependent during microbial infections, including parasitic infections." (PMID 31867283, 2019). "IL-21 and its cognate receptor, IL-21R, are highly expressed in parasitized organs of infected humans as well in murine models of the human parasitic diseases." (PMID 31867283, 2019). "The IL-21/IL-21R axis disruption also led to impaired resolution of parasitemia in the chronic phase of infection." (PMID 31867283, 2019). "Similar to Bcl6fl/flCD4-cre+/− and Sh2d1a−/− mice, Il21r−/− mice had an initial course of acute P. chabaudi infection with peak parasitemias at days 8–9." (PMID 28888925, 2017). "Although mice given WT CD8+ T cells reduced parasitemia after day 15, parasitemia levels steadily increased in mice receiving IL-21R KO CD8+ T cells." (PMID 27695083, 2016). "Similar to Il21-/- and Il21r-/- mice, mixed BM chimeric mice bearing Il21-/- T cells failed to control the chronic phase of infection and showed increasingly and sustained high parasitemias during this phase of infection." (PMID 25763578, 2015). "The presence of large numbers of Ter119+ rbc in the spleens of Il21-/- and Il21r-/- mice indicates increased hematopoiesis in response to anemia, presumably leading to production of many new rbc, which then controls the level of parasitemia." (PMID 25763578, 2015). "These high parasitemias were maintained in both Il21-/- and Il21r-/- after 120–150 days of infection (44±4% in Il21-/- and 56±3% in Il21r-/- mice at day 120 post-infection), without mortality." (PMID 25763578, 2015). "Similar to WT C57BL/6 mice, both Il21-/- and Il21r-/- mice had very low parasitemias by 11–14 days post-infection." (PMID 25763578, 2015). "Despite the tissue distribution and the omnipresence of IL-21 target cells in tissues in which protozoan and helminth parasites reside, the role of the IL-21/IL-21R signaling pathway in protection against and/or the promotion of inflammation during parasitic infections is not fully understood." (PMID 31867283, 2019). "Unveiling the IL-21/IL-21R crosstalk with other cytokine networks and their downstream genes will provide insight into the development of novel therapeutic targets for the parasite-induced immunopathology and the control of parasitic infections." (PMID 31867283, 2019). "Most studies investigating the roles played by the IL-21/IL-21R axis in parasitic infections, whether protective or detrimental, stemmed from reports in animal models." (PMID 31867283, 2019). "However, in stark contrast to WT mice, they developed sustained high parasitemias during the chronic phase of infection (e.g., parasitemias of 17% in Il21-/- and 23% in Il21r-/- mice compared with less than 0.04% in WT C57BL/6 at day 36 post-infection)." (PMID 25763578, 2015). "The impaired control of parasitemia and loss of the humoral response to P. chabaudi in Il21-/- and Il21r-/- mice were not due to lack of development of phenotypically-defined Tfh cells." (PMID 25763578, 2015). "The higher variability in the parasitemias in these mixed BM chimeric mice compared to Il21r-/- late in infection may reflect B-cell-independent alternate mechanisms, which require IL-21." (PMID 25763578, 2015).
parasitemia (continued). "Despite the failure of Il21-/- and Il21r-/- mice to resolve their chronic infection, they did not succumb to a fulminating parasitemia within the 100–150 days of the study." (PMID 25763578, 2015). "Similar to the P. chabaudi infection, both Il21-/- and Il21r-/- mice failed to clear a P. yoelii 17X(NL) erythrocytic infection, and developed sustained high parasitemias." (PMID 25763578, 2015). "Similar to the Il21r-/- mice, the mixed BM chimeric mice bearing Il21r-/- B cells eventually developed a non-resolving chronic-stage parasitemia." (PMID 25763578, 2015). "In stark contrast, both Il21-/- and Il21r-/- mice failed to resolve the second infection and showed sustained high parasitemias." (PMID 25763578, 2015). "Interestingly, neither Il21-/- nor Il21r-/- mice showed the peak of parasitemia characteristic of an acute primary infection after receiving the second P. chabaudi challenge, suggesting that some initial immune control could take place in the absence of an IgG B-cell response." (PMID 25763578, 2015). "Similarly, Il21r-/- mice also failed to resolve a second infection with P. yoelii 17X(NL), in contrast to WT C57BL/6 controls, which controlled parasitemias at very low levels." (PMID 25763578, 2015).
Autoimmunity (4 papers, 2018 to 2025). The occurrence of an immune reaction against the organism's own cells or tissues. "These varied actions may suggest that IL-21’s role in autoimmunity may depend on the cytokine milieu and IL21R variants." (PMID 40979706, 2025). "Presently, we cannot exclude that any of the differences observed in the frequency of dual-κ B cells in IL-21R KO mice are B cell-extrinsic and/or due to the absence of autoimmunity in these mice." (PMID 30266981, 2018).
Graves disease (4 papers, 2013 to 2023). Graves' disease is an autoimmune disorder that leads to overactivity of the thyroid gland (hyperthyroidism).It is caused by an abnormal immune system response that causes the thyroid gland to produce too much thyroid hormones. "In this study, we investigated whether polymorphisms of the IL-21 and IL-21R are associated with Graves’ disease (GD) and Hashimoto’s thyroiditis (HT), two major forms of AITDs, among a Chinese population." (PMID 23889847, 2013). "Furthermore, CD4+ IL-21R+ T cells and CD19+ IL-21R+ B cells were also observed in Graves’ disease tissues." (PMID 31412566, 2019). "IL-21 and IL-21R expression is upregulated in AITD, predominantly Graves' disease and Hashimoto's thyroiditis, and may be involved in the pathogenesis of AITD by enhancing the aberrant immune cascade, which indirectly affects thyroid function." (PMID 38022688, 2023).
Hashimoto thyroiditis (4 papers, 2013 to 2023). An autoimmune disorder caused by the production of autoantibodies against thyroid tissue. "SNPs of the IL-21 gene have been found to be associated with development of GD, while individuals with SNPs at the common IL-21 and IL-21R genes may present a higher risk of developing Hashimoto’s thyroiditis." (PMID 25667655, 2015).
liver disease (4 papers, 2017 to 2025). "However, certain patients with loss-of-function mutations in the IL-21R gene suffer from recurrent respiratory and gastrointestinal infections, additionally have cryptosporidiosis, leading to secondary cholangitis and liver disease according to some case reports." (PMID 38720319, 2024). "We also describe the clinical features of liver disease in some monogenic forms of PID included in the clinical spectrum of CVID as ICOS, NFKB1, NFKB2, CTLA-4, PI3Kδ pathway, ADA2, and IL21-R genetic defects." (PMID 32184784, 2020).
lymphoma (4 papers, 2013 to 2019). A malignant (clonal) proliferation of B- lymphocytes or T- lymphocytes which involves the lymph nodes, bone marrow and/or extranodal sites. "Importantly, similar to the mouse model, we show high expression of Grail and diminished expression of IL-21R in CD8+ T cells from lymphoma patients compared with healthy donors." (PMID 28798332, 2017). "Moreover, CD8+ T cells isolated from lymphoma patients express higher levels of Grail and lower levels of IL-21R, compared with CD8+ T cells from normal donors." (PMID 28798332, 2017). "Overall, this data suggest that the model described in the murine system where Grail expression is induced by TGF-β signalling and is involved in ubiquitination and degradation of the IL-21R may also occur in human patients with lymphoma." (PMID 28798332, 2017). "It should be noted however that IL-21 can trigger apoptosis of IL-21R-expressing lymphomas." (PMID 28615039, 2017). "We found that Grail expression in patients with lymphoma CD8+ T cells and mouse CD8+ TILs negatively correlates with IL-21R expression while expression of other receptors involved in common gamma chain cytokine signalling (IL-2R, IL-7R and IL-15R) did not depend on the level of Grail." (PMID 28798332, 2017). "Since rIL-21 (human) does not efficiently stimulate murine IL-21R, murine IL-21 (mIL-21) was used to test combinations with rituximab in disseminated lymphoma models using HS Sultan cells and Raji cells." (PMID 23825648, 2013). "In this same study, GRAIL was found to be increased and IL-21R decreased in PBMCs isolated from patients with lymphoma when compared with healthy donors, suggesting that targeting GRAIL clinically (most likely via a small molecule inhibitor) may be especially useful in the treatment of lymphoma." (PMID 31756921, 2019).
malaria (4 papers, 2015 to 2022). Malaria is a serious and sometimes fatal disease caused by a parasite that commonly infects a certain type of mosquito which feeds on humans. "Mice deficient in either IL-21 (Il21−/−) or IL-21R (Il21r−/−) were susceptible to rechallenge infections with homologous murine malaria parasites." (PMID 31867283, 2019). "For instance, studies have utilized P. berghei, a rodent malaria parasite, to analyze the extent to which the IL-21/IL-21R axis contributes to host immunity during CM in the murine hosts as a surrogate for the human disease." (PMID 31867283, 2019). "It demonstrated that IL21R was expressed in healthy individuals in malaria-endemic areas before the start of the malaria season and down-regulated a week after treatment of the first acute malaria episode (in convalescence), while TLR7, TLR9, PRDM1, and CD38 showed the opposite pattern." (PMID 36380692, 2022). "Analysis of PB CD21–/lowCD27– MBCs as bulk or the corresponding population in sc-RNAseq data from patients in a malaria-endemic area found high levels of AICDA, SYK, TNFRSF1B as well as IL21R, and IFNγ signature." (PMID 36380692, 2022).
asthma (3 papers, 2017 to 2021). "Mice deficient for IL21R had reduced airways eosinophilia in a model of mite-induced asthma, and knock-out mice for IL21R expressed higher levels of IgE and lower levels of IgG1 than normal mice after mite antigen exposure." (PMID 33692795, 2021). "Similar results showing a decline in AHR are also observed in an OVA-induced experimental asthma model using Il21r-deficient mice." (PMID 31921177, 2019). "However, Il21r-deficient mice develop unexpectedly less AHR in an HDM model of asthma." (PMID 31921177, 2019). "Although it is still not very clear why IL-21 and IL-21R signaling play different roles in asthma, it will be very exciting to see more studies provide definitive evidence on IL-21's immunomodulating functions in regulating TFH cells, IgE production, and germinal center response in asthma." (PMID 31921177, 2019).
COVID-19 (3 papers, 2021 to 2025). A disease caused by infection with severe acute respiratory syndrome coronavirus 2. "CoronaVac immunization increases HLA class II and IL21R expression in naïve B cells, whereas these markers are downregulated in severe COVID-19 cases." (PMID 40006648, 2025). "Significant differences were also detected in plasma levels of CXCL12, IL-17, TIMP-2 and IL-21R between mild and severe COVID-19 patients." (PMID 35087533, 2021). "Thus, low levels of its receptor, IL-21R, in severe COVID-19 could lead to an impaired IFN expression and facilitate the spread and replication of SARS-CoV-2." (PMID 35087533, 2021). "Genes related to T cell responsiveness such as IL21R, IL4R, CXCR4 were also upregulated in COVID-19-infected subjects." (PMID 36881624, 2023).
influenza (3 papers, 2013 to 2023). An acute viral infection of the respiratory tract, occurring in isolated cases, in epidemics, or in pandemics; it is caused by serologically different strains of viruses (influenzaviruses) designated A, B, and C, has a 3-day incubation period, and usually lasts for 3 to 10 days. "We previously observed that a protective humoral response to the influenza vaccine is associated with increased levels of IL-21 and increased expression of IL-21R in B cells post-vaccination." (PMID 24236161, 2013). "In a study of vaccine responses to the pandemic H1N1/09 influenza vaccine in HIV infected young patients, impaired vaccine responses were associated with defective function of pTfh and in the IL-21/IL-21R system." (PMID 24236161, 2013). "Since optimal clearance of IAV depends on both antibody-mediated virus neutralization and killing of influenza-infected cells by CD8+ T cells, we wanted to investigate what role, if any, IL-21R signaling played in a mouse model of IAV infection." (PMID 25849970, 2015). "We previously demonstrated in young HIV+ adults who responded to influenza vaccine that their plasma IL-21 levels increased with upregulation of IL-21R in B cells, while vaccine non-responders failed to do either." (PMID 24236161, 2013). "Interestingly, IL-21R levels in CD8 T lymphocytes remained unaltered, implying that mechanisms other than IL-21 are involved in the generation of influenza-specific CD8 T cells." (PMID 24236161, 2013).
ischemic stroke (3 papers, 2017 to 2024). A stroke disorder caused by obstruction of blood flow to the brain, due to thrombotic (local blood clot formation) or embolic (due to a blood clot or other material traveling from another site) event. "They found that IL-21R was exclusively expressed in neurons, and its expression was upregulated during ischemic stroke in both mouse model and human patients." (PMID 39472796, 2024). "This indicates a higher response can possibly be exerted by IL-21R-expressing neurons in response to IL-21 produced from infiltrated TFH cells during ischemic stroke." (PMID 39472796, 2024). "IL-21R plays a key role in neuronal protection through the JAK-STAT signaling pathway in ischemic stroke." (PMID 38154101, 2023). "Results from prior studies show that IL21R, BMF, and GPNMB correspond to mediators of injury following ischemic stroke." (PMID 28097054, 2017).